SNORD115-20 (small nucleolar RNA, C/D box 115-20)
Synonyms: HBII-52-20
Gene: Small nucleolar RNA gene on chromosome 15 (25,206,262 to 25,206,343, forward strand). Ensembl gene ENSG00000201969.
Gene Ontology:
Biological process: RNA processing
Cellular component: nucleolus
Homologues: Paralogues in human: SNORD115-12 (99% identical), SNORD115-9 (99% identical), SNORD115-10 (98% identical), SNORD115-11 (98% identical), SNORD115-13 (98% identical), SNORD115-17 (98% identical), SNORD115-18 (98% identical), SNORD115-19 (98% identical), SNORD115-29 (98% identical), SNORD115-36 (98% identical), SNORD115-40 (98% identical), SNORD115-42 (98% identical), and 37 more.